RTL8C (retrotransposon Gag like 8C)
Synonyms: CXX1; FAM127A; MAR8; MAR8C; MART8; SIRH5; MART8C
Tractability: PROTAC: ubiquitination databases record sites on it.
Gene: Protein-coding gene on chromosome X (135,032,355 to 135,033,546, forward strand). Ensembl gene ENSG00000134590.
Subcellular location: Cell membrane
Homologues: Orthologues: mouse Rtl8a (72% identical), mouse Rtl8b (72% identical), rat Rtl8a (72% identical), mouse Rtl8c (64% identical). Paralogues in human: RTL8A (94% identical), RTL8B (93% identical), LDOC1 (55% identical), RTL6 (35% identical), PEG10 (31% identical), RTL3 (31% identical), RTL5 (30% identical), RTL1 (29% identical), RTL10 (29% identical), RTL4 (11% identical).
Diseases named in the same sentence as RTL8C in open-access papers:
RTL8C is named in the same sentence as 2 diseases in open-access papers, as found by Europe PMC text mining. Sharing a sentence is not in itself a finding about the gene and the disease.
RTL8C shares sentences with these, for which no sentence is quoted: tumor (2 papers); amyotrophic lateral sclerosis (1).